DAD1 (defender against cell death 1)
Description:
Subunit of the oligosaccharyl transferase (OST) complex that catalyzes the initial transfer of a defined glycan (Glc(3)Man(9)GlcNAc(2) in eukaryotes) from the lipid carrier dolichol-pyrophosphate to an asparagine residue within an Asn-X-Ser/Thr consensus motif in nascent polypeptide chains, the first step in protein N-glycosylation. N-glycosylation occurs cotranslationally and the complex associates with the Sec61 complex at the channel-forming translocon complex that mediates protein translocation across the endoplasmic reticulum (ER). All subunits are required for a maximal enzyme activity (By similarity). Required for the assembly of both SST3A- and SS3B-containing OST complexes. Loss of the DAD1 protein triggers apoptosis.
Synonyms: OST2
Tractability: Small molecule: a structure with a bound ligand is known. Antibody: UniProt predicts a signal peptide or a membrane-spanning region. PROTAC: ubiquitination databases record sites on it; its protein half-life has been measured.
Gene: Protein-coding gene on chromosome 14 (22,564,902 to 22,589,235, reverse strand). Ensembl gene ENSG00000129562.
Subcellular location: Endoplasmic reticulum membrane
Subcellular location (Human Protein Atlas): Cytosol; Endoplasmic reticulum
Pathways (Reactome):
Disease: Maturation of DENV proteins; Maturation of spike protein
Cell-Cell communication: Regulation of CDH1 posttranslational processing and trafficking to plasma membrane
Immune System: PD-L1(CD274) glycosylation and translocation to plasma membrane
Metabolism of proteins: Asparagine N-linked glycosylation
Gene Ontology:
Molecular function: enzyme activator activity
Biological process: protein N-linked glycosylation; regulation of protein stability; glycoprotein biosynthetic process; negative regulation of apoptotic process
Cellular component: membrane; oligosaccharyltransferase complex; oligosaccharyltransferase complex A; oligosaccharyltransferase complex B; endoplasmic reticulum membrane
Genetic constraint (gnomAD): Loss-of-function variants: 4 observed, 9.55 expected, observed/expected ratio (o/e) 0.42, 90% interval 0.2 to 0.96. That is too few expected variants to judge how well the gene tolerates losing a copy. Missense variants: 119 observed, 147.25 expected, observed/expected ratio (o/e) 0.81, 90% interval 0.7 to 0.94. Synonymous variants: 60 observed, 67.79 expected, observed/expected ratio (o/e) 0.89, 90% interval 0.72 to 1.1.
Homologues: Orthologues: chimpanzee DAD1 (100% identical), macaque DAD1 (100% identical), mouse Dad1 (100% identical), rabbit DAD1 (100% identical), rat Dad1 (100% identical), dog DAD1 (99% identical), guinea pig Dad1 (99% identical), pig DAD1 (99% identical), tropical clawed frog dad1 (83% identical), zebrafish dad1 (77% identical), Drosophila melanogaster Dad1 (63% identical), Caenorhabditis elegans dad-1 (58% identical).
Diseases named in the same sentence as DAD1 in open-access papers:
DAD1 is named in the same sentence as 23 diseases in open-access papers, as found by Europe PMC text mining. Sharing a sentence is not in itself a finding about the gene and the disease. The quoted sentences say what the papers report.
breast carcinoma (2 papers, 2017 to 2021). "Based on the results of the present study, we suggest the use of HSP90AB1, DAD1, PFN1 and PUM1 in any combination of threes (triplet) for normalization of the expression of genes of interest in SK-BR-3 breast cancer cell line." (PMID 34681026, 2021).
hepatocellular carcinoma (2 papers, 2017 to 2021). A malignant tumor that arises from hepatocytes. "In fact, DAD1 was preferentially expressed in hepatocellular carcinoma (HCC) and prostate cancer cells." (PMID 34681026, 2021).
acute lymphoblastic leukemia (1 paper, 2021). Leukemia with an acute onset, characterized by the presence of lymphoblasts in the bone marrow and the peripheral blood. "There are not many reports known that link DAD1 to acute lymphoblastic leukemia progression and proliferation, except one that reported its anti-apoptotic role in leukemic cells." (PMID 34072627, 2021).
adrenocortical tumors (1 paper, 2024). "Among other DEPs, several have known roles in cancer (e.g. Dad1 and Brd9), adrenocortical tumors (Gnas), and cytochrome c oxidase subunits (e.g. Cox6c2 and Cox7a2l)." (PMID 38864697, 2024).
asthma (1 paper, 2015). "DAD1 is active in the apoptosis regulation process and its failure in this process may lead to increased lymphocytes in asthma patients." (PMID 26635092, 2015). "Furthermore, based on described biological functions, it is reasonable to suppose that genes which are potentially associated with asthma symptoms may be located in this region, with the example of SLC7A7, MMP14 and DAD1." (PMID 26635092, 2015).
esophageal cancer (1 paper, 2024). A primary or metastatic malignant neoplasm involving the esophagus. "The Mendelian randomization results indicate a causal relationship between genes such as CTSZ, CTSC, DAD1, COLEC12, ATOX1 in the TUBA1B+Mac-C0 cluster and the occurrence of esophageal cancer." (PMID 38434988, 2024).
ovarian carcinoma (1 paper, 2024). A malignant neoplasm originating from the surface ovarian epithelium. "Upon correlating our study's findings with the existing literature, we observed that silencing FGF8 in ovarian cancer cells resulted in the downregulation of several proteins associated with cancer progression, including SLC7A5, FHL2, SPATS2L, and DAD1." (PMID 39309198, 2024). "The expression of DAD1 in ovarian cancer was reported in OVCAR3 cells following the treatment of cisplatin, indicating that over-expression of DAD1 contributed to the development of cisplatin resistance in ovarian cancer." (PMID 39309198, 2024).
schizophrenia (1 paper, 2017). A major psychotic disorder characterized by abnormalities in the perception or expression of reality. "These include: VAT‐1, DAD‐1, PAQR9, BCKD, BDH, Prickle4, PP2A, RPL13A, SPRED2, KLP, FAM36A, NAB1, CLSTN3, PEDF‐R, and FZD3 (Frizzled gene previously associated with different psychopathologies, most notably Schizophrenia)." (PMID 27696737, 2017).
cancer (9 papers, 2007 to 2024). A tumor composed of atypical neoplastic, often pleomorphic cells that invade other tissues. "Then, risk scores were calculated for every cancer sample calculated by using the following formula: Riskraw = DAD1*2.316+CYCS*1.426+CSNK2A2*1.576+VPS25*0.728+VDAC1*0.976+TMLHE*0.381+CYTH3*0.024+PRKCA*0.260-TP73*0.567+FZD6*0.047+SQSTM1*0.094-MAP2K7*3.070." (PMID 35185897, 2022). "As for DAD1, it is a negative regulator of cell death associated with the endoplasmic reticulum cell death pathway that has been linked to tumorigenesis in various cancers." (PMID 38918490, 2024). "CCL5, a ligand of CCR5, is a product of cancer itself and its microenvironment, using the mTOR pathway through the regulation of cyclin D1, c-Myc, and Dad-1 expression to enhance tumor growth." (PMID 39329983, 2024). "This is consistent with the known important role of glycosylation in Notch signaling, suggesting that in cancer cell driven by NOTCH1 mutation, high DAD1 expression level indicates high dependence on its function." (PMID 31039782, 2019). "The class of verified anti-apoptotic molecules overexpressed in cancer includes prominent tumor-associated proteins such as β-Catenin (CTNNB1), Osteopontin (OPN/SPP1), BMI1, Peroxiredoxin 3 (PRDX3;) and DAD1." (PMID 23717670, 2013). "As the name suggests DAD1 is anti-apoptotic and can be upregulated in cancer." (PMID 18710513, 2008). "CenpA, dad1, BI-1 and MIF are also overexpressed in human cancers." (PMID 17311107, 2007).
tumor (5 papers, 2013 to 2025). "Another downregulated protein DAD1 is a negative regulator of apoptosis, and tumor cells may benefit from its ability to prevent apoptosis from continuing to grow indefinitely." (PMID 39309198, 2024). "Many therapeutic targets—such as GAD1, DAD1, and MMP9—are also expressed in normal tissues, raising concerns about off-tumor toxicity." (PMID 41050070, 2025). "Hence, it has been postulated that high expression of DAD1 in HCC cells can activate OST and block apoptosis, thereby enhancing tumor cell survival." (PMID 34681026, 2021).
infection (3 papers, 2019 to 2025). The state of being infected such as from the introduction of a foreign agent such as serum, vaccine, antigenic substance or organism. "It is possible that JcDAD1 may function in adjusting the balance between reproductive development and stress response via the JA synthetic pathway because DAD1 can simultaneously act in flower development and wound defense and inhibit pathogen infection." (PMID 33255510, 2020). "In both animals and plants, the expression of DAD1 orthologs responds to a wide range of adverse environmental stimuli, including injury, temperature, and pathogen infection." (PMID 30800138, 2019).
epithelial carcinoma (1 paper, 2021). "In A431 epithelial carcinoma cells, DAD1 was upregulated in hypoxic conditions (by a fold change of 1.2) after exposure of 72 h." (PMID 34681026, 2021).
DAD1 also shares sentences with these, for which no sentence is quoted: bladder cancer (2 papers); Alzheimer disease (1); COVID-19 (1); HIV-1 infection (1); Insulin resistance (1); leukemia (1); mantle cell lymphoma (1); neurological diseases (1); Obesity (1); prostate carcinoma (1); stomach cancer (1).